DUSP5P1 (dual specificity phosphatase 5 pseudogene 1)
Synonyms: FLJ34941; formerly DUSP5P
Gene: Processed pseudogene on chromosome 1 (228,650,241 to 228,651,379, forward strand). Ensembl gene ENSG00000183929.
Diseases named in the same sentence as DUSP5P1 in open-access papers:
DUSP5P1 is named in the same sentence as 11 diseases in open-access papers, as found by Europe PMC text mining. Sharing a sentence is not in itself a finding about the gene and the disease. The quoted sentences say what the papers report.
gastric cancer (5 papers, 2022 to 2026). A primary or metastatic malignant neoplasm involving the stomach. "DUSP5P1 was found to be highly expressed in gastric cancer and was linked to poor prognosis in multiple myeloma." (PMID 37686617, 2023). "Furthermore, studies have shown that the up-regulation of dual specificity phosphatase 5 pseudogene 1 (DUSP5P1) is linked to reduced survival in two separate cohorts of gastric cancer patients." (PMID 41362671, 2026). "The study discovered that DUSP5P1 boosted the migration and invasion of gastric cancer cells during in vitro experiments and their metastatic potential in an animal model." (PMID 41362671, 2026). "A previous study confirmed that C8orf76 acted as a tumor-promoting role in gastric cancer that transactivated lncRNA DUSP5P1 by directly binding to the DUSP5P1 promoter and activating the MAPK/ERK signaling pathway." (PMID 35884471, 2022). "We demonstrated that gastric cancer (GC) patients with high DUSP5P1 expression had shortened survival in two independent cohorts." (PMID 36307394, 2022). "Taken together, these results validate the pro-metastatic role of DUSP5P1 in gastric cancer." (PMID 41362671, 2026). "In addition, DUSP5P1 promotes platinum resistance in gastric cancer cell lines by activating the ERK1/2 signaling pathway." (PMID 38927012, 2024). "Consistent with this, up-regulation of DUSP5P1 in gastric cancer cells neutralized the cytotoxic effects of oxaliplatin, while silencing DUSP5P1 combined with oxaliplatin treatment demonstrated a synergistic effect in inhibiting metastasis of gastric cancer both in vitro and in vivo." (PMID 41362671, 2026). "Further analysis shows that DUSP5P1 activates the ARHGAP5 gene, which in turn stimulates focal adhesion and MAPK signaling pathways to enhance gastric cancer metastasis." (PMID 41362671, 2026).
Burkitt lymphoma (1 paper, 2014). A rare form of malignant mature B-cell non-Hodgkin lymphoma. "Cells from other tumor types (Burkitt's lymphoma, leukemia, neuroblastoma, Ewing sarcoma) also showed a higher DUSP5P1/DUSP5 ratio than normal cells." (PMID 24651368, 2014).
gastric tumors (1 paper, 2022). "High DUSP5P1 expression was found in 33.04% (37/112) of primary gastric tumors in cohort I, and 36.79% (39/106) in cohort II, respectively." (PMID 36307394, 2022). "DUSP5P1 expression was also significantly higher in metastatic lesions as compared to primary gastric tumors (P < 0.05)." (PMID 36307394, 2022). "DUSP5P1 expression was significantly increased in primary gastric tumors as compared with adjacent non-tumor tissues (P < 0.01)." (PMID 36307394, 2022).
germ cell tumor (1 paper, 2014). A benign or malignant, gonadal or extragonadal neoplasm that originates from germ cells. "The simultaneous presence of DUSP5P1 transcripts and ERV transcripts in testicular germ cell tumor cells and HL cells suggests that in both cell types transcription is deregulated in a similar way." (PMID 24651368, 2014).
tumor (5 papers, 2014 to 2022). "After stratification by tumor staging, high DUSP5P1 predicted poor prognosis in stage I-II GC patients both in Cohort I (P = 0.0201) and in Cohort II (OS, P = 0.0203; PFS, P = 0.0482)." (PMID 36307394, 2022). "In conclusion, our study reported for the first time that lncRNA DUSP5P1 is a novel tumor metastasis-promoting factor in GC." (PMID 36307394, 2022). "The molecular mechanisms of DUSP5P1 as a tumor-promoting factor involved direct induction of the tumor promoting factor ARHGAP5, resulting in the activation of focal adhesion and MAPK signaling pathways." (PMID 36307394, 2022). "In this study, we found that DUSP5P1 is highly expressed in GC tumor tissues." (PMID 36307394, 2022). "Thus, DUSP5P1 plays an important tumor promoting role in gastric metastasis through dysregulated oncogenic signaling pathways, especially focal adhesion and MAPK signaling." (PMID 36307394, 2022). "We then tested whether the inhibition of focal adhesion or MAPK pathways could blunt the tumor-promoting effect of DUSP5P1." (PMID 36307394, 2022). "Further investigation is required to determine the role of DUSP5P1 in regulating DUSP5 function, and whether DUSP5P1 expression correlates with the prognosis of or tumor remission in NB." (PMID 30866462, 2019). "In the current study, we observed a decrease in methylation following the MBC2 intervention, which may indicate an upregulation of DUSP5P1 and tumor suppression." (PMID 31506096, 2019). "Hence, DUSP5P1 exerts the tumor-promoting effect by activating focal adhesion and MAPK signaling." (PMID 36307394, 2022). "Thus, the DUSP5/DUSP5P1 system could be responsible for regulation of BCL2L11 leading to inhibition of apoptosis in these tumor cells." (PMID 24651368, 2014). "DUSP5P1 is highly expressed in Hodgkin’s lymphoma cell lines and several tumor types, but not in normal blood cells." (PMID 36307394, 2022). "Quantitative RT-PCR indicated high expression of DUSP5P1 not only in HL cells but also in other tumor cells from hematopoietic and non-hematopoietic malignancies." (PMID 24651368, 2014). "The complete spectrum of transcripts form the DUSP5P1/ERVK_1q42.13 locus in HL cells and other tumor cells has not been determined." (PMID 24651368, 2014).
cancer (3 papers, 2019 to 2025). A tumor composed of atypical neoplastic, often pleomorphic cells that invade other tissues. "High DUSP5P1 expression predicted a higher risk of cancer-related death by univariate Cox regression analysis (Cohort I: P = 0.014; Cohort II: P = 0.006)." (PMID 36307394, 2022). "We demonstrated that DUSP5P1 caused significant dysregulation of signaling pathways, in particular, focal adhesion and MAPK signaling, which are the key regulating pathways of cancer progression and metastasis." (PMID 36307394, 2022). "In another study, the expression in human cancer cells of DUSP5 and the DUSP5 pseudogene DUSP5P1 was compared, showing high ratios of DUSP5P1/DUSP5 expression in cancer cell lines, including NB cell lines, when compared to normal tissues." (PMID 30866462, 2019).
DUSP5P1 also shares sentences with these, for which no sentence is quoted: Ewing sarcoma (1 paper); leukemia (1); lung adenocarcinoma (1); multiple myeloma (1); neuroblastoma (1).